THAP6 (THAP domain containing 6)
Synonyms: MGC30052
Tractability: PROTAC: ubiquitination databases record sites on it.
Gene: Protein-coding gene on chromosome 4 (75,513,946 to 75,550,473, forward strand). Ensembl gene ENSG00000174796.
Subcellular location (Human Protein Atlas): Centrosome; Nucleoplasm
Gene Ontology:
Molecular function: protein binding
Cellular component: microtubule cytoskeleton
Genetic constraint (gnomAD): Loss-of-function variants: 15 observed, 22.46 expected, observed/expected ratio (o/e) 0.67, 90% interval 0.45 to 1.03. The upper end of that interval is the gene's LOEUF score, 1.03, which puts it in group 4 of 6, group 1 being the genes least tolerant of losing a copy. Missense variants: 262 observed, 274.42 expected, observed/expected ratio (o/e) 0.95, 90% interval 0.86 to 1.06. Synonymous variants: 93 observed, 96.78 expected, observed/expected ratio (o/e) 0.96, 90% interval 0.81 to 1.14.
Homologues: Orthologues: chimpanzee THAP6 (99% identical), dog THAP6 (91% identical), pig THAP6 (91% identical), rat Thap6 (84% identical), rabbit THAP6 (83% identical), macaque THAP6 (68% identical), zebrafish ftr97 (24% identical), zebrafish zgc:113019 (23% identical), zebrafish si:dkey-60a16.1 (23% identical), zebrafish si:ch211-262i1.5 (22% identical), zebrafish si:dkey-56d12.4 (18% identical), tropical clawed frog c8h14orf28 (17% identical), and 7 more. Paralogues in human: THAP3 (14% identical), THAP7 (12% identical), THAP1 (12% identical), THAP8 (11% identical), THAP2 (10% identical), ARL14EP (6% identical), ARL14EPL (2% identical).
Diseases named in the same sentence as THAP6 in open-access papers:
THAP6 is named in the same sentence as 3 diseases in open-access papers, as found by Europe PMC text mining. Sharing a sentence is not in itself a finding about the gene and the disease. The quoted sentences say what the papers report.
HIV-1 infection (1 paper, 2015). The type species of lentivirus and the etiologic agent of acquired immunodeficiency syndrome (AIDS). "Other pseudogene:gene pairs with modulating gene expression in early and late HIV-1 infection, but with unknown roles in viral infection, are RP11-380G5.3:DOK1 and RP11-114F3.5:THAP6." (PMID 26426037, 2015).
THAP6 also shares sentences with these, for which no sentence is quoted: cancer (1 paper); viral infection (1).